TTR (transthyretin)
Diseases named in the same sentence as TTR in open-access papers (continued):
Sharing a sentence is not in itself a finding about the gene and the disease.
familial amyloid polyneuropathy (continued). "Hereditary transthyretin-related amyloidosis (ATTRv amyloidosis) is a rare and progressively debilitating disease characterized by the deposition of transthyretin (TTR) amyloid fibrils in various organs and tissues, most commonly in the heart and peripheral nerves." (PMID 38907862, 2024). "Our findings demonstrate that bone scintigraphy might detect favorable treatment effect of patisiran in ATTRv amyloidosis patients and possible disease progression in ATTRv amyloidosis patients treated with a TTR-stabilizer at low dose." (PMID 37843599, 2024). "Therapeutic modalities for ATTRv amyloidosis encompass a range of interventions, including transthyretin tetramer stabilizers such as Tafamidis, pharmacotherapies targeting transthyretin reduction like Patisiran, and surgical interventions such as liver transplantation." (PMID 39286810, 2024). "While patients with ATTRwt predominantly present with cardiac phenotypes (i.e., TTR cardiomyopathy [ATTR-CM]), patients with ATTRv present with various types of phenotypes that can be predominantly neuropathic (i.e., TTR familial amyloid polyneuropathy [ATTR-PN]), cardiac (i.e., ATTR-CM) or mixed." (PMID 39472905, 2024). "Disease-modifying treatments (DMTs) such as tafamidis meglumine (transthyretin stabilizer), patisiran, vutrisiran (small-interfering RNA), and inotersen (antisense oligonucleotide) have been approved for the treatment of ATTRv amyloidosis by multiple regulatory agencies." (PMID 37828588, 2023). "Hereditary transthyretin (ATTRv) amyloidosis with polyneuropathy, also known as familial amyloid polyneuropathy (FAP), represents a progressive, heterogeneous, severe, and multisystemic disease caused by pathogenic variants in the TTR gene, which is ultimately fatal." (PMID 37830598, 2023). "Thus, pioneering clinical studies include RNAi drugs targeting liver synthesis of PCSK9, resulting in highly significant lowering of LDL cholesterol or targeting liver transthyretin (TTR) synthesis for treatment of cardiac TTR amyloidosis." (PMID 36615135, 2023). "Here, we investigated whether there is a difference in the amount of TTR aggregates and EV markers in S-EVs between patients with hereditary ATTRv amyloidosis and the healthy controls." (PMID 35402512, 2022). "The enhanced cellular deposition of TTR aggregates by EVs indicates that the EV-mediated tissue deposition of TTR aggregates may be involved in ATTRv amyloidosis as well as Alzheimer’s disease." (PMID 35402512, 2022). "Furthermore, the amount of TTR aggregates in serum-derived small EVs in patients with ATTRv amyloidosis was lower than that in healthy controls." (PMID 35402512, 2022). "Human serum EVs (S-EVs) collected by ultracentrifugation contain TTR amyloid; however, it remains unknown whether EVs contribute to TTR aggregation, deposition, or clearance in hereditary ATTRv amyloidosis." (PMID 35402512, 2022). "It has been recently found that TTR amyloid deposits of type A (composed of the full length and truncated TTR forms) in the heart tissue sections of patients with systemic TTR amyloidosis were accompanied by Ca2+ depositions of unique characteristics and unusual morphology." (PMID 35987087, 2022). "Nevertheless, DNA sequencing of the TTR gene can be a useful approach in patients with idiopathic neuropathy to support or exclude a diagnosis of ATTRv amyloidosis and for predictive genetic counseling testing in healthy but potentially at-risk persons with a family history of ATTRv amyloidosis." (PMID 31907599, 2021). "Therefore, researchers have developed several strategies for therapeutic intervention of TTR amyloidosis; e.g., liver transplantation procedures for hereditary TTR amyloidosis, and RNAi-based approaches to modulate the overall expression of TTR plasma protein." (PMID 33800546, 2021).
familial amyloid polyneuropathy (continued). "Targeted delivery of intrathecally administered therapeutics has just recently begun to play a role in ATTRv amyloidosis: Alnylam Pharmaceuticals has conducted pre-clinical studies, using murine models for targeted ocular TTR transcript knockdown (Nair_OTS2018 (alnylam.com))." (PMID 34719408, 2021). "For example, we propose that their high affinity toward TTR may compromise their functionality as effective TRβ activators, resulting in reduced multi-functional activity as a therapeutic molecule for TTR amyloidosis, or related pathologies." (PMID 33800546, 2021). "In recent years, it has been shown that tolcapone is a potent inhibitor of the amyloid aggregation process of the transthyretin protein, and acts through stabilizing the structure of the protein, reducing the progression of a disease called familial amyloid polyneuropathy." (PMID 32708961, 2020). "However, TTR also is an amyloidogenic protein responsible for familial amyloid polyneuropathy (FAP) and familial amyloid cardiomyopathy (FAC)." (PMID 32419519, 2020). "In ATTRv amyloidosis patients who undergo liver transplantation, cardiac amyloidosis may progress even after transplantation due to wild-type TTR deposition, particularly in elderly male patients." (PMID 30764529, 2019). "Transthyretin familial amyloid polyneuropathy is suspected when patients develop progressive peripheral sensory-motor neuropathy, associated with family history of neuropathy (94%) and/or autonomic dysfunction, or gastrointestinal disorder (40−48% in early onset)." (PMID 31452024, 2019). "The TTR gene is located on chromosome 18q12.1 and consists of 4 exons and 5 introns; the 2 distinct types of ATTR are differentiated according to the TTR mutation: hereditary TTR amyloidosis (ATTRm) and wild-type TTR amyloidosis (ATTRwt)." (PMID 31718691, 2019). "In addition, gene-silencing drugs that significantly reduce the amount of TTR produced in the liver have also become available for ATTRv amyloidosis." (PMID 30764529, 2019). "TTR-related hereditary amyloidosis is divided into two categories depending on the tissue that is predominantly affected: familial amyloid polyneuropathy (FAP), which mainly affects the peripheral nervous system, and familial amyloid cardiomyopathy (FAC), which predominantly affects the heart." (PMID 27050398, 2016). "With prolonged durations, overexpression of TTR might accumulate in human tissue as seen in several pathologies including familial amyloid polyneuropathy, Alzheimer disease, and cardiomyopathy." (PMID 27741252, 2016). "This study evaluated the safety, tolerability, pharmacokinetics, and pharmacodynamics of multiple doses of patisiran (ALN-TTR02), a small interfering RNA encapsulated within lipid nanoparticles, in patients with transthyretin-mediated familial amyloid polyneuropathy (FAP)." (PMID 26338094, 2015). "Cardiologists may encounter TTR amyloidosis in patients who are referred with neurologic impairment or previously diagnosed TTR-FAP, and in patients who present with cardiologic problems without any apparent signs of neurologic disease." (PMID 23425518, 2013). "We believe this finding may have relevance in the context of several diseases i.e. senile systemic amyloidosis, familial amyloid polyneuropathy and familial amyloid cardiomyopathy, where high levels of monomeric TTR are present." (PMID 20927353, 2010). "Moreover, TTR deposits can co-exist with β-amyloid ones in patients with ATTRv amyloidosis." (PMID 37784196, 2023). "The decrease in tetramer TTR in blood serum may manifest the disease onset of TTR amyloidosis." (PMID 36776255, 2023). "The detection of TTR in urine may become a useful biomarker for ATTRv amyloidosis." (PMID 35893595, 2022).
familial amyloid polyneuropathy (continued). "Interaction between amyloid proteins and extracellular vesicles (EVs), which are secreted by various cells, is known to promote the clearance of the proteins, but it is unclear whether EVs are involved in the formation and deposition of TTR amyloid in ATTRv amyloidosis." (PMID 35402512, 2022). "We propose that a stabilization of physiological aggregation-resistant αSH in PD and DLB patients may be beneficial in slowing down the process of neurodegeneration, analogous to efforts currently underway toward stabilizing transthyretin in familial amyloid polyneuropathy." (PMID 35141810, 2022). "Hereditary transthyretin amyloidosis (ATTRv amyloidosis) is a rare, autosomal-dominant (AD) multisystem disorder resulting from the extracellular deposition of amyloid fibrils formed by a destabilized mutant form of transthyretin (TTR), a transport protein predominantly produced by the liver." (PMID 35463150, 2022). "Hereditary transthyretin amyloidosis (ATTRv amyloidosis) is a rare and debilitating multisystem disorder resulting from the extracellular deposition of amyloid fibrils formed by a destabilized mutant form of transthyretin (TTR), a transport protein predominantly produced by the liver." (PMID 35463150, 2022). "Furthermore, we observe a decrease in TTR in serum-derived EVs in patients with hereditary ATTRv amyloidosis, indicating that EVs could play an active role in TTR tissue deposition." (PMID 35402512, 2022). "The substitution of valine for methionine at position 30 (V30M) in the TTR polypeptide chain was the first mutation to be identified and, is the most common mutation associated with ATTR polyneuropathy (ATTR-PN) (previously designated familial amyloid polyneuropathy—FAP)." (PMID 33362465, 2020). "Therefore, identification of compounds that exhibit TTR fertilization inhibitory or TTR amyloid fibril disrupting activities might be potential candidates for the development of therapeutic agents in TTR amyloidosis." (PMID 30704121, 2019). "Beyond TTR hereditary amyloidosis, non-coding variants associated with TTR expression could be involved in the pathogenesis of the non-inherited form of TTR amyloidosis, known as senile systemic amyloidosis." (PMID 28335735, 2017). "Tafamidis, an oral drug that acts as a small molecule stabilizer of TTR tetramers has been approved for the treatment of familial amyloid polyneuropathy (FAP) and ATTR-CA." (PMID 36776255, 2023). "In patients with familial amyloid polyneuropathy (FAP), IDOX co-localized with amyloid deposits and in vitro broke down TTR fibrils from patients into an amorphous precipitate." (PMID 31546787, 2019). "In vivo, subcutaneous infusion of CLR01 on a transgenic mouse model of Familial Amyloid Polyneuropathy (FAP) restored the TTR plasma level to healthy conditions, significantly reduced TTR extracellular accumulation in several organs and rescued tissue damage." (PMID 31075983, 2019). "It was extensively used thereafter and is found in two additional marketed ASOs: inotersen/Tegsedi and volanesorsen/Waylivra, which respectively target TTR and APOC3 genes and have been approved for the treatment of familial amyloid neuropathies and familial chylomicronemia, respectively." (PMID 35213992, 2022). "Similar non-fibrillar TTR deposits have also been reported in transgenic mouse and rat models of ATTRv amyloidosis." (PMID 34443678, 2021). "Recently, nonsurgical options have emerged to treat familial amyloid polyneuropathy (FAP), including stabilizer therapies (tafamidis and diflunisal) and transthyretin silencers (inotersen and patisiran)." (PMID 35497887, 2022).
polyneuropathy (196 papers, 2010 to 2026). A disease or disorder affecting more than one nerve. "This is comparable to the TTR decrease with patisiran q3w (83–84%) in the APOLLO Phase 3 investigation, where the magnitude of TTR decrease was linked to enhancement in polyneuropathy and a broad spectrum of clinical symptoms." (PMID 40331977, 2025). "Our study aimed to report the clinical features and epidemiological characteristics of hereditary transthyretin amyloidosis-polyneuropathy(ATTRv-PN) with TTR Ala97Ser(p.Ala117Ser) mutation from South Mainland China." (PMID 40296002, 2025). "A valine to methionine substitution at position 30 (V30M) in TTR is one of the most common mutations associated with polyneuropathy." (PMID 40564999, 2025). "Transthyretin (TTR) variant (V30M) polyneuropathy (ATTRv-PN) is a progressive systemic amyloidosis caused by transthyretin aggregation, leading to a variety of debilitating manifestations, including neuropathy and cardiomyopathy." (PMID 40564999, 2025). "Participants were classified into symptomatic patients with polyneuropathy (n = 31) and asymptomatic TTR variant carriers (n = 41)." (PMID 41153229, 2025). "The findings of this study highlight the comparative performance of two widely used immunoassay platforms, SiMoA and Ella, in measuring serum NfL levels in symptomatic ATTRv subjects with polyneuropathy and presymptomatic subjects harboring TTR variants." (PMID 40462552, 2025). "It develops when inherited genetic mutations synthesise dysfunctional transthyretin protein, which accrues and disrupts organs, typically causing cardiac failure or polyneuropathy." (PMID 41583176, 2025). "There were 17 patients (15 [88%] men) with clinically and electrophysiologically defined polyneuropathy caused by TTR A97S mutation." (PMID 37902278, 2024). "A total of 112 subjects enrolled in the EMPATIa study, 105 were eligible, 19 of whom were Coutinho stage 1 polyneuropathy ATTRv patients and 86 AC of a pathogenic mutation in the TTR gene." (PMID 39242501, 2024). "Hereditary transthyretin amyloidosis with polyneuropathy (ATTRv‐PN) is caused by mutations in the TTR gene, leading to misfolded monomers that aggregate generating amyloid fibrils." (PMID 37725003, 2024). "Although drugs from both of these classes have been approved for TTR-related polyneuropathy, siRNA has been associated with effectiveness against ATTR-CM in patients with mixed disease." (PMID 38541013, 2024). "In our study, the proband with the homozygous TTR c.302C>T variant had the most pronounced polyneuropathy with tetraparesis." (PMID 38399526, 2024). "The study involved 168 adult participants diagnosed with Coutinho stage 1 or 2 ATTRv polyneuropathy and possessing a confirmed TTR variant." (PMID 39684857, 2024). "Amyloid deposits as well as toxic TTR monomers and oligomers cause extensive tissue damage, mostly leading to polyneuropathy and cardiomyopathy." (PMID 38622453, 2024). "The most common pathogenic TTR variant causing ATTRv polyneuropathy is c.148G>A, p.(Val50Met) (previously known as Val30Met), which is endemic in some regions of Portugal, Sweden and Japan." (PMID 38399526, 2024). "The individual with the homozygous c.302C>T TTR variant had the most pronounced polyneuropathy with tetraparesis." (PMID 38399526, 2024). "Patients enrolled had Coutinho stage 1 or 2 ATTRv-PN, a documented TTR sequence variant, and signs/symptoms of polyneuropathy." (PMID 37901600, 2023). "To conclude, the TTR Ser77Tyr mutation causes a rare disease with typical but common presenting symptoms, usually due to a median and polyneuropathy, and cardiomyopathy." (PMID 36772971, 2023). "The clinical study that evaluated the efficacy and the safety profile of this drug is APOLLO-B, a randomized, double-blind, placebo-controlled study that gathered 225 patients with a TTR mutation and polyneuropathy." (PMID 36983602, 2023).
polyneuropathy (continued). "Transthyretin tetramer stabilization was confirmed also upon oral treatment with tafamidis meglumine 20 mg once daily in patients with ATTRv with polyneuropathy and mutations other than Val30Met in 100% of evaluable patients." (PMID 36555787, 2022). "hATTR can manifest with a predominant polyneuropathy or cardiomyopathy phenotype, or a mixture of both, depending on the TTR variant." (PMID 35908242, 2022). "In older individuals, wild-type TTR protein is prone to aggregation, causing cardiac disease, whereas a variety of destabilizing TTR variants can lead to cardiomyopathy or polyneuropathy." (PMID 37123434, 2022). "Patients with FAP carrying the mutation TTR c.401A>G (p.Tyr134Cys), first reported in Japan, manifested polyneuropathy, vitreous opacities and cardiopathy." (PMID 35627273, 2022). "Inotersen, an antisense oligonucleotide inhibitor of hepatic TTR production, demonstrated a favorable efficacy and safety profile in patients with the polyneuropathy associated with hATTR in the NEURO-TTR (NCT01737398) study." (PMID 35908242, 2022). "It would be important to study other well‐characterized pathogenic mutations of the TTR gene which are implicated in ATTR amyloidosis with a predominant polyneuropathy phenotype." (PMID 36575133, 2022). "Hereditary amyloidosis associated with transthyretin (ATTRv), is a rare autosomal dominant disease characterized by length-dependent symmetric polyneuropathy that has gait impairment as one of its consequences." (PMID 35887731, 2022). "Hereditary transthyretin amyloidosis with polyneuropathy (ATTRv) is caused by mutations in the TTR gene, leading to misfolded monomers that aggregate generating amyloid fibrils." (PMID 35295833, 2022). "Certain TTR mutations are associated predominantly with endoneurial amyloid deposition that results in polyneuropathy (most commonly Val30Met); others are associated with predominant cardiomyopathy or a mixed phenotype." (PMID 31907599, 2021). "In peripheral sensorimotor neurons, ATTR deposits are causing polyneuropathy, which are, together with cardiomyopathy, the major clinical manifestations of TTR amyloidosis." (PMID 34035264, 2021). "In a large study of one of the most common pathogenic TTR mutations, the V122I variant was significantly associated with polyneuropathy diagnosis." (PMID 34079032, 2021). "Hereditary transthyretin amyloidosis (ATTR), caused by TTR gene mutations, is characterized by a length-dependent polyneuropathy and autonomic dysfunction, with multisystem involvement, namely, the heart, eyes, and kidney." (PMID 35185758, 2021). "These patients have variants in the TTR gene that lead to aggregation of transthyretin protein, resulting in a multisystemic disorder that includes polyneuropathy and cardiac problems." (PMID 32391605, 2021). "In contrast, late onset TTR V30M patients show loss of both small and large fibers, less severe polyneuropathy, mild autonomic dysfunction and frequent cardiomegaly." (PMID 30875761, 2019). "The first human study of tafamidis for the treatment of polyneuropathy associated with TTR mutations was reported in 2012." (PMID 26664897, 2015). "Diagnosis is based on family history, neurographic evidence of polyneuropathy, detection of mutated TTR or DNA in the blood, and identification of amyloid deposits in the tissues (mainly in intestinal, nerve, salivary gland or abdominal fat biopsies)." (PMID 24572009, 2014). "In FAP, deposition of aggregated TTR protein is a pathological hallmark of a polyneuropathy and subsequent peripheral neurodegeneration." (PMID 21375738, 2011). "Familial amyloidotic polyneuropathy (FAP), now more commonly known asvariant transthyretin amyloidosis(ATTRv), encompassing polyneuropathy (ATTRv-PN) and cardiomyopathy (ATTRv-CM), is a progressive and life-threatening disorder caused by mutations in thetransthyretin(TTR) gene." (PMID 40541194, 2025).